DNAH12 (dynein axonemal heavy chain 12)
Description:
Involved in spermiogenesis. Plays a role in the proper organization of axoneme in sperm flagella, but not in cilia, by recruiting DNAH1 and DNALI1 to flagellum.
Synonyms: DHC3; DLP12; DNAH12L; DNAH7L; DNAHC3; DNHD2; HDHC3; HL19; HL-19; FLJ40427; FLJ44290; DLP3; DNAHC12; SPGF100
Tractability: Small molecule: a structure with a bound ligand is known.
Gene: Protein-coding gene on chromosome 3 (57,293,699 to 57,544,344, reverse strand). Ensembl gene ENSG00000174844.
Subcellular location: Cell projection, cilium, flagellum
Subcellular location (Human Protein Atlas): Centrosome; Mid piece; Principal piece; Cytosol
Gene Ontology:
Molecular function: ATP binding; dynein intermediate chain binding; dynein light intermediate chain binding; minus-end-directed microtubule motor activity
Biological process: sperm axoneme assembly; spermatid development; microtubule-based movement
Cellular component: sperm flagellum; axonemal dynein complex; dynein complex; motile cilium
Genetic constraint (gnomAD): Loss-of-function variants: 255 observed, 342.09 expected, observed/expected ratio (o/e) 0.75, 90% interval 0.67 to 0.83. The upper end of that interval is the gene's LOEUF score, 0.83, which puts it in group 3 of 6, group 1 being the genes least tolerant of losing a copy. Missense variants: 3,438 observed, 3,642.7 expected, observed/expected ratio (o/e) 0.94, 90% interval 0.92 to 0.97. Synonymous variants: 1,160 observed, 1,217.5 expected, observed/expected ratio (o/e) 0.95, 90% interval 0.91 to 1.
Gene-disease validity (ClinGen):
ClinGen rates the evidence that DNAH12 causes each of these diseases.
spermatogenic failure (autosomal recessive): Definitive. A male infertility characterized by dirsuption of the process of sperm development from diploid cells into mature haploid spermatozoa.
Homologues: Orthologues: chimpanzee DNAH12 (99% identical), pig DNAH12 (92% identical), dog DNAH12 (92% identical), rabbit DNAH12 (91% identical), mouse Dnah12 (89% identical), rat Dnah12 (89% identical), tropical clawed frog dnah12 (77% identical), zebrafish dnah12 (73% identical), macaque DNAH12 (11% identical). Paralogues in human: DNAH7 (53% identical), DNAH3 (51% identical), DNAH1 (42% identical), DNAH6 (36% identical), DNAH2 (34% identical), DNAH10 (32% identical), DNAH17 (31% identical), DNAH9 (31% identical), DNAH11 (30% identical), DNAH5 (29% identical), DNAH14 (29% identical), DNAH8 (29% identical), and 3 more.
Diseases named in the same sentence as DNAH12 in open-access papers:
DNAH12 is named in the same sentence as 5 diseases in open-access papers, as found by Europe PMC text mining. Sharing a sentence is not in itself a finding about the gene and the disease. The quoted sentences say what the papers report.
male infertility (4 papers, 2024 to 2025). The inability of the male to effect fertilization of an ovum after a specified period of unprotected intercourse. "Seven mutations in DNAH12 were identified as potential pathogenic factors for male infertility in patients P1-3 of family 1, P4-5 of family 2, P8 of family 3, and P9, P10, and P11, all of whom suffered from asthenoteratozoospermia." (PMID 40146200, 2025). "Furthermore, we demonstrate that bi-allelic mutations in DNAH12 are identified as causative factors for asthenoteratozoospermia and male infertility in both humans and mice." (PMID 40146200, 2025). "Mutations of DNAH3 and DNAH12 are linked to male infertility and dynein dysfunction in humans." (PMID 40568142, 2025). "Mutations of DNAH12 cause male infertility by impairing DNAH1 and DNALI1 recruitment." (PMID 40568142, 2025). "Through comprehensive genetic analyses involving whole-exome sequencing and subsequent Sanger sequencing on infertile patients and fertile controls from six distinct families, we unveiled six biallelic mutations in DNAH12 that co-segregate recessively with male infertility in the studied families." (PMID 40146200, 2025). "Two mouse models, Dnah12-/- and Dnah12mut/mut, were generated and exhibited asthenoteratozoospermia and male infertility, mimicking our patients’ phenotypes." (PMID 40146200, 2025). "Currently, 13 members of the DNAH gene family have been reported, including DNAH1 to DNAH3, DNAH5 to DNAH12, DNAH14, and DNAH17, among which 11 genes (DNAH1, DNAH2, DNAH5 to DNAH12, and DNAH17) are associated with male infertility." (PMID 38312775, 2024). "Deficiency of DNAH12 leads to the failure of DNALI1 and DNAH1 recruitment to sperm flagella, resulting in abnormal sperm morphology characterized by compromised axoneme organization, causing male infertility." (PMID 40146200, 2025). "Additionally, other DNAHs, such as DNAH1, DNAH2, DNAH8, DNAH10, DNAH12, and DNAH17, are suggested to be pathogenic genes of isolated male infertility." (PMID 39503742, 2024).
asthenozoospermia (1 paper, 2025). "The expression pattern of DNAH12 in testes suggests that it is possibly involved in spermiogenesis, and its abnormal expression could lead to asthenozoospermia or asthenoteratozoospermia, further indicating that the identified DNAH12 mutations are candidate pathogenic mutations for patients." (PMID 40146200, 2025).
cervical carcinoma (1 paper, 2021). A carcinoma arising from either the exocervical squamous epithelium or the endocervical glandular epithelium. "The increased sample size enabled identification of SMGs previously unreported in cervical carcinoma including NBPF10 (8%), RANBP2 (6%), MSN (6%), KRT8 (6%), POTEC (6%), ZC3H11A (4%), BMS1 (4%), GPX1 (3%), OTOP1 (3%), DNAH12 (2%), COIL (2%), TBC1D26 (2%), SPRED3 (2%), FAM115A (2%), and ARIH1 (1%)." (PMID 34620846, 2021).
hypospadias (1 paper, 2025). Hypospadias is the displacement of the urethral meatus on the ventrum of the penis. "Additionally, we detected variants of uncertain significance in hypospadias-related gene families (DNAH12 and LHFP) and in other genes, such as COL6A3, which may cause the phenotype." (PMID 41300791, 2025). "Although DNAH12 has not been directly implicated in hypospadias, its role in ciliary function and sperm motility suggests potential relevance to male reproductive development." (PMID 41300791, 2025). "Although rare damaging variants in several dynein heavy chain genes have been linked to hypospadias, DNAH12 itself has not been specifically implicated, and a recent study found no enrichment of DNAH12 mutations in severe hypospadias cases compared with the controls." (PMID 41300791, 2025). "However, current human data do not indicate a significant enrichment of DNAH12 variants in hypospadias cases." (PMID 41300791, 2025).
Infertility (1 paper, 2025). "Mutations of DNAH12 have been predicted to be associated with male patients' infertility, however, limited pathogenic evidence was provided, and the underlying pathogenesis remained unclear." (PMID 40146200, 2025). "Previously, two genetic screening studies mentioned unverified compound heterozygous mutations and a homozygous missense mutation in DNAH12, predicting their association with patients’ infertility." (PMID 40146200, 2025). "Utilizing whole-exome sequencing (WES) followed by Sanger sequencing, we identified six novel bi-allelic mutations in DNAH12 in infertile males from six unrelated families." (PMID 40146200, 2025). "In our study, the successful ICSI outcomes of Dnah12-/- mice suggest that ICSI could be used as a potential treatment for infertile men carrying Dnah12 mutations." (PMID 40146200, 2025). "Identification of bi-allelic DNAH12 variants in infertile men with asthenoteratozoospermia." (PMID 40146200, 2025). "Clinical characteristics of the infertile patients with bi-allelic DNAH12 mutations." (PMID 40146200, 2025). "Moreover, the infertility of Dnah12-/- mice could be overcome by intracytoplasmic sperm injection (ICSI) treatment." (PMID 40146200, 2025).